ALB (albumin)
Diseases named in the same sentence as ALB in open-access papers (continued):
Sharing a sentence is not in itself a finding about the gene and the disease.
myeloma (continued). "In the present work, we show that azacytidine-treatment induces necrosis of myeloma cells through oxidative stress, and that necrotic myeloma cells exhibit unique characteristics, including enrichment of cell-bound albumin and overexpression of the ER- and mitochondrial-specific chaperones." (PMID 23764212, 2013). "The nuclear area, form factor, FD and goodness-of-fit did not correlate with ISS stage or laboratory parameters, such as serum calcium concentration, β2-microglobulin, albumin, creatinine, hemoglobin value, PB platelet count and BM percentage of myeloma cells (Spearman rank order test)." (PMID 21698234, 2011). "In 1990, a study of 612 patients enrolled on a Southwest Oncology Group trial confirmed that serum beta-2 ­microglobulin was the most robust prognostic factor for myeloma, and that the prognostic value could be improved further by combining with albumin and age." (PMID 40973877, 2025). "Wide differences between total urine protein and urine albumin may indicate the presence of large amounts of monoclonal proteins, but this “proteinuria gap” has been shown to be unreliable in diagnosing multiple myeloma but could be helpful in the diagnosis of myeloma cast nephropathy." (PMID 39457572, 2024). "Finally, increased levels of IgA-albumin complexes due to prolonged half-life may promote hyperviscosity syndrome, a major complication in patients with multiple myeloma characterized by abnormal IgA production." (PMID 33578917, 2021). "Immunoglobulin A (IgA)-albumin complexes may be associated with pathophysiology of multiple myeloma, although the etiology is not clear." (PMID 33578917, 2021). "Thus, IgA-albumin complexes may accumulate in body fluids during multiple myeloma, leading to complications such as hyperviscosity syndrome." (PMID 33578917, 2021). "Therefore, in this study, to better understand the pathophysiology of multiple myeloma and hyperviscosity syndrome, we performed a detailed structural analysis of the IgA-albumin complex produced in multiple myeloma patients using proteomics and bioinformatics technologies." (PMID 33578917, 2021). "Moreover, the levels of biological markers, including albumin, creatinine, and hemoglobin (Hb) and myeloma status including lactate dehydrogenase, beta 2‐microglobulin (B2M), ISS, and R‐ISS were relatively lower in the patients with social frailty than those without social frailty." (PMID 35847687, 2020). "Albumin, a component of both the CONUT score and ISS, can be influenced by inflammatory cytokines like IL-6 from the myeloma microenvironment and changes in body fluid volume." (PMID 40003698, 2025). "MM, multiple myeloma; df, degrees of freedom; P, Probability; Hb, hemoglobin; Cr, creatinine; Ca, calcium; β2-MG, serum beta-2-microglobulin; ALB, albumin; LDH, lactate dehydrogenase." (PMID 40259951, 2025). "Recognizing this, the International Myeloma Working Group (IMWG) accumulated data from 10 750 patients across 17 countries and devised the ISS which combined 2 simple prognostic values, albumin and beta-2 microglobulin." (PMID 40973877, 2025). "Our CD38-specific HLE-nano-BiKEs all showed specific binding to CD38 on myeloma cells, CD16 on NK cells, and to human albumin." (PMID 35651607, 2022). "We verified specific and simultaneous binding to CD38 on myeloma cells, CD16 on NK cells, and to albumin." (PMID 35651607, 2022). "A variety of biomarkers are considered for diagnosis (e.g., β2-microgobulin, albumin, or LDH) and prognosis [e.g., cytogenetic aberrations detected by fluorescence in situ hybridization (FISH)] of multiple myeloma (MM)." (PMID 35928862, 2022). "However, it is not known whether oxidized albumin is associated with the pathophysiology of multiple myeloma or its complications." (PMID 33578917, 2021). "As a result, it is reasonable to believe that albumin and LDH level are related to the activity of myeloma cells." (PMID 34103001, 2021).
myeloma (continued). "The R-ISS divides myeloma patients into the stages I-III depending on four different biomarkers (serum ß2–microglobulin, serum albumin, chromosomal abnormalities, and serum LDH)." (PMID 32825035, 2020). "This is further supported by significantly less production of IgG, IgA, and IgM as well as minimal reduction in albumin synthesis in MGUS compared to smoldering multiple myeloma and multiple myeloma." (PMID 31940353, 2020). "The most extensively employed prognostic system in myeloma is the ISS, a system which stratifies patients into three groups, as determined by serum albumin and β2-microglobulin levels." (PMID 25624913, 2015). "In conclusion, our results suggest that in the setting of acute dialysis-dependent myeloma cast nephropathy due to elevated kappa FLC, HDF with 2.2 m2 heat sterilized high-flux polyphenylene HF could be used as an alternative to HCO-dialysis with a lower albumin loss." (PMID 26466100, 2015). "Specifically, in a cohort of 190 newly diagnosed multiple myeloma patients, we have examined the behaviour of RDW and its trend in relation to the ISS stage and other prognostic factors, such as albumin, beta-2 microglobulin, LDH and bone marrow plasma cell infiltration." (PMID 38310176, 2024). "The label free data also showed a couple of non-IgG related proteins that undergo dysregulation in multiple myeloma, among them being albumin and APOA1, aligning with established literature." (PMID 37835457, 2023). "In multiple myeloma, serum β2M level is the main determinant of the International Staging System (ISS, Stage I: β2M < 3.5 mg/dl and albumin > 3.5 g/dl, Stage II: β2M > 3.5 but less than 5.5 mg/dl or β2M < 3.5 mg/l and albumin < 3.5 g/dl, Stage III β2M > 5.5 mg/l)." (PMID 28664159, 2017). "Therefore, in patients with acute dialysis-dependent myeloma cast nephropathy, in addition to chemotherapy, HDF with a heat sterilized high-flux polyphenylene HF dialyzer could offer an alternative to HCO dialysis for extracorporeal kappa reduction with lower albumin loss." (PMID 26466100, 2015). "Unfortunately, the described methods have their limitations because albumin is not the only carrier of calcium, which becomes more important when cancer cells produce paraproteins that can bind calcium (especially important in the case of multiple myeloma)." (PMID 38920679, 2024). "Lab tests found urine protein and decreased serum albumin, without evidence of myeloma." (PMID 23231829, 2012). "Therefore, the IgA-oxidized albumin complex may be associated with the pathophysiology of complications in patients with multiple myeloma characterized by abnormal IgA production, although the physiological roles of oxidized albumin have not been elucidated." (PMID 33578917, 2021). "Similarly, no significant trends in percentage of myeloma infiltration in the bone marrow were noted regarding laboratory results, including LDH, serum M protein, albumin, CRP, and uric acid." (PMID 36769265, 2023).
pulmonary edema (76 papers, 2006 to 2025). Accumulation of fluid in the lung tissues causing disturbance of the gas exchange that may lead to respiratory failure. "Albumin therapy in acute ischemic stroke has shown potential benefits, but it is also associated with significant adverse effects, including pulmonary edema and increased mortality rates." (PMID 40332503, 2025). "Low albumin also leads to a decrease in the plasma osmotic pressure, which is more likely to cause pulmonary edema." (PMID 38028763, 2023). "In HRS-AKI patients with increased risk factors for pulmonary edema, caution is required because of the combined effects of albumin infusion and terlipressin." (PMID 38139434, 2023). "This may be attributed to potential adverse effects such as pulmonary edema and cerebral hemorrhage, linked to albumin’s antiplatelet effects, hemodilution of coagulation factors, and calcium-binding properties." (PMID 41468394, 2025). "A decrease in serum albumin levels can exacerbate fluid retention and tissue oedema, particularly pulmonary oedema, which may increase the risk of developing acute respiratory distress syndrome." (PMID 39927140, 2025). "When administering albumin (20–40 g/day), it must be considered that this therapeutic approach carries a risk of developing pulmonary edema, which may further impair respiratory function in already critically ill patients with ACLF." (PMID 41007756, 2025). "The application of fibrinogen might be helpful to reduce the risk of re-bleeding, and albumin is frequently used to increase the oncotic pressure in blood to optimize systolic blood pressure and avoidance of cerebral and/or pulmonary edema." (PMID 35887976, 2022). "A large proportion of critically ill patients present increased capillary fragility and extravasation of albumin to interstitial areas, which may cause pulmonary edema." (PMID 21181070, 2010). "For instance, a meta-analysis of albumin use in patients with spontaneous bacterial peritonitis reported significant benefit that was not seen in patients with other infections, and this latter trial was terminated because of lethal pulmonary edema associated with albumin." (PMID 37019645, 2023). "In fact, pulmonary edema occurred in a notable percentage of patients, and higher mortality rates were observed in the albumin-treated groups." (PMID 40332503, 2025). "The albumin dosage is also reduced/stopped if pulmonary oedema develops following the albumin treatment." (PMID 38551716, 2024). "The targeted albumin treatment group showed more severe or life-threatening complications due to the treatment, including the development of pulmonary oedema and multiorgan failure." (PMID 38551716, 2024). "When administering albumin infusions, we recommend careful monitoring of vital signs during and after albumin infusions, which can be complicated by pulmonary edema and high blood pressure." (PMID 36269406, 2023). "Despite its widespread use in AKI in cirrhotic patients, the optimal albumin dose is uncertain, and one should be particularly vigilant about the possibility of iatrogenic pulmonary edema with the use of higher doses." (PMID 37510105, 2023). "In patients with acute ischemic stroke, adverse events related to albumin infusion were those related to volume overload leading to acute heart failure or pulmonary edema." (PMID 36337861, 2022). "Albumin clearance from the alveolar space is essential for the recovery from pulmonary edema because increased protein osmotic pressure slows alveolar fluid clearance (AFC)." (PMID 35955955, 2022). "The first inhibitor studied was the plasma protein albumin, a prominent component of high molecular weight pulmonary edema." (PMID 26793419, 2016). "More than one century ago, Reisman and Hartkey used the terms of "albuminous expectoration" and "albumin sputum" in cases that developed pulmonary edema after removal of a large amount of pleural fluid." (PMID 19638221, 2009).
pulmonary edema (continued). "In a dose-escalation study of 25% albumin treatment in 82 patients with acute ischemic stroke, mild or moderate pulmonary edema was observed in 13% of the patients." (PMID 18318896, 2008). "Severe edema, shock, and pulmonary edema may occur, requiring careful fluid management, albumin infusion, and cautious diuretic use." (PMID 40283525, 2025). "This improvement may stem from albumin's role in elevating colloid osmotic pressure, thereby diminishing alveolar and capillary permeability and lessening pulmonary edema." (PMID 39169930, 2024). "However, the adverse effects of albumin, such as aggravating pulmonary edema, should also be considered." (PMID 35694666, 2022). "Finally, we did not collect the adverse events resulting from albumin infusion, but our study excluded the specific population that had a possible adverse event for albumin use, such as systolic heart failure and severe pulmonary edema." (PMID 36337861, 2022). "Lower albumin facilitates transudation of fluids and increases incidence of pulmonary edema." (PMID 31097889, 2019). "Only in patients with albumin < 2 g/dL with hypovolaemia and/or pulmonary oedema." (PMID 28979337, 2017). "Two prior studies investigating the efficacy of albumin for non-SBP infections have previously suggested the risk of pulmonary edema." (PMID 26178624, 2015). "How albumin affects alveolar epithelial Na+ transport is currently unknown, despite the common use of albumin in cell culture and for AFC measurement as well as its presence in the alveolar lining fluid and association with pulmonary edema." (PMID 35955955, 2022). "Nevertheless, treatment with intravenous ALB did not improve IS outcome and may even cause pulmonary edema and intracerebral hemorrhage." (PMID 34829993, 2021). "In addition, the guidelines still include generalized recommendations regarding withdrawal of diuretics and plasma volume expansion with albumin for 48 h, which may be ineffective and counterproductive and may have iatrogenic effects, such as fluid overload and acute cardiogenic pulmonary edema." (PMID 38726210, 2024). "The 28-day mortality rate was similar between groups, and 22% of patients in the albumin group discontinued the treatment due to adverse effects (primarily pulmonary edema or bronchospasm) compared to no patients in the PlasmaLyte group." (PMID 40386509, 2025). "The ATTIRE (Albumin to Prevent Infection in Chronic Liver Failure) trial involving IV albumin administration in hospitalized patients targeting albumin >3 g/dL showed that it did not improve outcomes; however, it increased the risks of AKI and pulmonary edema." (PMID 38202206, 2023). "However, post-discharge albumin draws remained associated with 1.6-fold higher likelihood of other vs. no readmission, and post-discharge hemoglobin/hematocrit draws remained associated with 1.7-fold higher risk of pulmonary edema-related vs. no readmission (not statistically significant)." (PMID 30064380, 2018). "Albumin and IgG are present in pulmonary edema fluid in concentrations that are 40–65% of plasma levels in hydrostatic pulmonary edema and 75–95% in non-cardiogenic pulmonary edema." (PMID 29354115, 2017). "Unlike the vasoconstrictors, adverse events attributable to albumin infusion have been reported only very infrequently in the included and other studies, and these have been related to pulmonary edema and/or circulatory overload." (PMID 26606982, 2015). "Thus, rapid albumin infusion has become a relative contraindication of CS in primary health care without sufficient ability to monitor pulmonary oedema." (PMID 35694666, 2022). "Among those with albumin drawn immediately post-hospitalization, those who were readmitted due to pulmonary edema-related or other reasons vs. not readmitted had lower average albumin values (3.57 g/dl in both readmitted groups vs. 3.67 g/dl in the non-readmitted group)." (PMID 30064380, 2018).
pulmonary edema (continued). "Due to its oncotic properties and non-oncotic properties, albumin may decrease the extravasation of fluid from vessels into interstitial spaces and thus reduce the degrees of pulmonary edema and improve oxygenation." (PMID 25474401, 2014). "At present, although albumin treatment has been suggested to improve oxygenation transiently in ARDS patients, no sufficient evidence justifies its use to mitigate pulmonary edema and reduce respiratory morbidity." (PMID 21906342, 2011). "However, the ALIAS trial’s findings indicated that high-dose albumin in AIS patients failed to improve outcomes, possibly due to complications like pulmonary edema." (PMID 40353064, 2025).
glomerular disease (75 papers, 2011 to 2025). "Hypervolemia and oedema result from primary salt retention and glomerular filtration rate (GFR) reduction due to glomerulopathy, which leads to urinary protein loss, increased tubular albumin reabsorption, and enhanced salt and water retention." (PMID 40511270, 2025). "Future research will facilitate understanding the role of Akt signaling in PTEC apoptosis and tubulointerstitial injury thus progression of glomerular diseases and how this process is linked to albumin endocytosis." (PMID 40313745, 2025). "Some glomerular diseases, such as minimal change disease, cause fusion of glomerular epithelial cell foot processes, resulting in predominantly “selective” loss of albumin." (PMID 38376552, 2024). "Other glomerular diseases can present with disruption of the basement membrane and slit diaphragms (e.g., by immune complex deposition), leading to marked loss of albumin and other plasma proteins." (PMID 38376552, 2024). "The risk of glomerular disease was increased with younger age, females, and steroid free induction and lower pretransplant serum albumin." (PMID 28951873, 2017). "While proteinuria and glomerulopathy are known risk factors for DN, the impact of serum albumin levels on kidney function remains unclear." (PMID 38774257, 2024). "Loss of albumin via urine is a key clinical marker for glomerular diseases." (PMID 38791159, 2024). "Even early glomerular disease and loss of size and charge permselectivity in DM with increased albumin leakage may not cause microalbuminuria, if normal proximal tubular function can remove the excess albumin from the glomerular filtrate." (PMID 28840540, 2017). "The study included adult patients with NS (plasma albumin levels < 25 g/L and urine albumin-creatinine ratio > 2,200 mg/g) with a primary glomerular disease compared with healthy individuals." (PMID 41333097, 2025). "Despite possessing a high-capacity megalin-cubilin receptor complex, albumin concentration in the glomerular filtrate often reaches beyond the endocytic capacity of PTEC in glomerular diseases." (PMID 40313745, 2025). "Glomerular‐type proteinuria with increased urinary excretion of albumin often signals glomerular injury such as recurrent or de novo glomerulopathies, transplant glomerulopathy (TG) or hypertension‐induced glomerulopathy of the allograft." (PMID 41286586, 2025). "In this study, we show that expression of survival protein Akt is downregulated in PTEC in response to albumin overload and in human glomerular disease." (PMID 40313745, 2025). "Hemodynamic changes such as an increased GFR and albumin excretion accompanied by glomerulopathy led to podocyte cell damage and mesangial enlargement." (PMID 36644578, 2023). "A better understanding of the fate of filtered albumin probably explains some discrepancies, such as the common phenomenon of glomerulopathy sans proteinuria." (PMID 36139492, 2022). "The individual impact of the many variables affecting proteinuria and their associations, including glomerulopathy, hyperfiltration, RFR and protein intake, and tubular albumin reclaiming capacity are only partially understood." (PMID 36139492, 2022). "Urinary albumin, also becomes present in the urine in response to stress to renal tubules and after various glomerulopathies and in mice has been detected as early as 4 h after AKI induction." (PMID 36541220, 2022). "Increased urinary albumin excretion is a key feature of glomerular disease but has limitations as a measure of glomerular permeability." (PMID 29433915, 2018). "The knowledge of the mechanisms involved in albumin handling in podocytes is a fundamental element not only to understand pathogenesis of glomerulopathies but also to identify novel drug targets." (PMID 29057905, 2017). "Celastrol-albumin nanoparticles thus represents a promising treatment option for mesangioproliferative glomerulonephritis and similar glomerular diseases." (PMID 29026082, 2017).